DEFA5 (defensin alpha 5)
Diseases named in the same sentence as DEFA5 in open-access papers (continued):
Sharing a sentence is not in itself a finding about the gene and the disease.
tumor (15 papers, 2004 to 2025). "Tumor sections were stained with antibodies to DEFA5 and epithelial cell adhesion molecule (ECad) to evaluate the integrity of tumor tissue." (PMID 38182890, 2024). "Considering its tumor-suppressive function and its known immunomodulating role of DEFA5, the detection of DEFA5 even in healthy donors is reasonable and has also been reported earlier." (PMID 35267585, 2022). "S100P, S100A2 and MMP12 were expressed higher in tumor tissues, compared with normal tissues (P < 0.001), while the opposite was true for DEFA5 expression (P < 0.05)." (PMID 35831362, 2022). "Via binding with BMI1 protein, DEFA5 could exert anti-tumor effects by inhibiting the cell mitosis." (PMID 35296002, 2022). "All these indicated that DEFA5 may have a specific tumor inhibitory effect." (PMID 34635074, 2021). "Moreover, the differential roles of specific defensins (e.g., tumor-suppressive DEFA5 vs. tumor-promoting DEFA6) highlight the complexity of AMP regulation in CRC and suggest that targeted modulation of AMP pathways could represent a novel therapeutic strategy for CRC." (PMID 40585846, 2025). "Among the co-expressed genes shared by DEFA5 and DEFA6, KLK12, which is responsible for tumor formation, was highly expressed in CRC." (PMID 36703795, 2022). "CK20 and DEFA5 mRNA expression was determined in MNC fractions from blood and bone marrow taken pre-operatively before tumor resection of a cohort of 216 EC patients." (PMID 35267585, 2022). "The shMLL1 human Ls174T xenografts and sphere cells showed enhanced differentiation with an increase in the expression of the Paneth cell-specific genes DEFA5 and LYZ and the goblet cell markers MUC2 and ITF, as was also observed in the β-catGOF mouse tumor model." (PMID 33349639, 2020). "Mechanistically, DEFA5 induces cell cycle arrest by binding to BMI1, reducing its binding to the CDKN2a locus and upregulating the expression of the cyclin-dependent kinase inhibitors p16 and p19, therefore significantly increasing the number of cells in the G1 phase and inhibiting tumor growth." (PMID 36275647, 2022). "The expression levels of DEFA1–3 were correlated to lymphatic or hepaticmetastasis.HNP1-3 were expressed in tumor cells rather than in neutrophils.DEFA5 were found inhibit progression of CRC and maybe a favorable prognostic factors." (PMID 36703795, 2022). "High proliferative goblet cells expressing MKI67 and metaplastic paneth cells expressing antimicrobial α‐defensins (DEFA5 and DEFA6) were enriched in precancerous and tumor tissues comparing with adjacent tissues, suggesting they might play a role in tumorigenesis." (PMID 34185431, 2021). "In our collective, gender, age, different tumor entities, and UICC stage did not correlate with CK20 or DEFA5 expression in blood or bone marrow samples of EC patients." (PMID 35267585, 2022).
infection (12 papers, 2011 to 2025). The state of being infected such as from the introduction of a foreign agent such as serum, vaccine, antigenic substance or organism. "In contrast to the mature gastrointestinal tract where DEFA5 is expressed at high levels in both states of health and infection/inflammation, our quantitative real-time PCR data demonstrate that DEFA5 expression in the kidney is significantly up-regulated with infection." (PMID 22359618, 2012). "Ileal RNA expression of the alpha-defensin AMPs, Defa5, and Defa6, as well as MMP7, was significantly lower in Ptpn2∆IEC vs. Ptpn2fl/fl mice, after mAIECred but not K12 infection." (PMID 40955058, 2025).
cancer (11 papers, 2010 to 2024). A tumor composed of atypical neoplastic, often pleomorphic cells that invade other tissues. "DEFA5 is likely to increase passively with the progression of cancer and has the effect of inhibiting cancer." (PMID 36703795, 2022). "For DEFA5, the expression levels in early-stage cancer patients (median: 3.41 [EU], range: 0–138.00 [EU]) were comparable to patients with late-stage cancer (median: 3.57 [EU], range: 0–61.73 [EU]) (p = ns) and thus were comparable to those of IID patients." (PMID 35008210, 2021). "Moreover, CRC patients also exhibited significantly elevated DEFA5 expression levels; however, with no discriminatory differences between early (UICC I+II) and late (UICC III+IV) stage cancer." (PMID 35008210, 2021).
kidney disease (1 paper, 2020). "However, the roles of the encoded proteins of DEFA5/6 which were called intestinal antimicrobial peptides HD5 and HD6 were not clear in kidney disease, such as IgAN." (PMID 32089753, 2020).
DEFA5 also shares sentences with these, for which no sentence is quoted: adenocarcinoma (2 papers); cholera (1); COVID-19 (1); Crohn ileitis (1); Crohn's colitis (1); duodenal cancer (1); epithelial dysplasia (1); meningioma (1); rectal adenocarcinoma (1).